SAA2-SAA4 (SAA2-SAA4 readthrough)
Gene: Protein-coding gene on chromosome 11 (18,231,423 to 18,248,635, reverse strand). Ensembl gene ENSG00000255071.
Genetic constraint (gnomAD): Loss-of-function variants: 13 observed, 17.84 expected, observed/expected ratio (o/e) 0.73, 90% interval 0.47 to 1.16. The upper end of that interval is the gene's LOEUF score, 1.16, which puts it in group 5 of 6, group 1 being the genes least tolerant of losing a copy. Missense variants: 156 observed, 198.98 expected, observed/expected ratio (o/e) 0.78, 90% interval 0.69 to 0.89. Synonymous variants: 67 observed, 64.02 expected, observed/expected ratio (o/e) 1.05, 90% interval 0.86 to 1.28.